MYC (MYC proto-oncogene, bHLH transcription factor)
Diseases named in the same sentence as MYC in open-access papers (continued):
Sharing a sentence is not in itself a finding about the gene and the disease.
plasmacytoma (22 papers, 2007 to 2024). Plasmacytoma is a localized mass of neoplastic monoclonal plasma cells that represents approximately 5% of all plasma cell neoplasms. "The prominence of these tumors is majorly due to the amplification of the MYC oncogene, which fuses with the plasmacytoma variant translocation 1 (PVT1), which stabilizes the MYC proteins." (PMID 38391759, 2024). "LncRNA PVT1, an activator of MYC, was first identified in plasmacytoma variant translocations in mice in 198431." (PMID 33067424, 2020). "The plasmacytoma variant translocation 1 (PVT1) gene encodes a lncRNA and was first discovered as an activator of MYC in murine plasmacytoma variant translocation in 1984." (PMID 31309249, 2019). "One locus at 8q24.21 comprised the representative oncogenes of myelocytomatosis (MYC) and plasmacytoma variant translocation 1 (PVT1) (4.5%)." (PMID 24944681, 2014). "The human PVT1 lncRNA is located on chromosome 8 telomeric to the c-Myc gene and is frequently involved in the translocations occurring in variant Burkitt’s lymphomas and murine plasmacytoma; PVT1 presents two MYC-binding sites in its promoter, which are bound and transactived by c-MYC." (PMID 29739426, 2018). "At first, lncRNA PVT1 was discovered as an activator of MYC in mouse plasmacytoma translocation, and later it was found that lncRNA PVT1 played a carcinogenic part in various human cancers." (PMID 35399100, 2022). "There has been an insufficient number of studies devoted to the investigation of c-MYC in the tumour substrate of plasmacytoma." (PMID 32321465, 2020). "It seemed interesting to us to estimate the expression of the c-MYC protein in bone and extramedullary plasmacytoma cells." (PMID 32321465, 2020). "Anti-CD56, anti-CD166, anti-CXCR4, anti-Ki-67, and anti-c-MYC antibodies were used for IHC study of plasmacytoma biopsies." (PMID 32321465, 2020). "Concomitant expression of MYC and deregulated IL-6 led to a more rapid plasmacytoma occurrence in a mouse model." (PMID 32329469, 2019). "The lack of pro- apoptotic signals or the enriched survival signals carried by crossed Tg facilitated MYC driven plasmacytoma-genesis by increasing PC frequency in normal mice and increased cyclin D expression." (PMID 29732008, 2018). "In the present work, we show the potent activity of EDO-S101 in MM cell lines, in MM cells from patients, in a subcutaneous plasmacytoma xenograft model, and in the clinically predictive VK*MYC murine model." (PMID 28633670, 2017). "This activity was confirmed in vivo, in a CB17-SCID murine plasmacytoma model and in de novo Vk*MYC mice, leading to a significant survival improvement in both models." (PMID 28633670, 2017). "Plasmacytoma can be differentiated from PBL, where the former lacks MYC gene rearrangement." (PMID 37777745, 2023). "In the spleens of Vk*MYC mice, most plasma cells stained weakly for Ki67, indicating that these cells were not plasmacytoma cells, which are generally proliferative." (PMID 31277689, 2019). "MYC rearrangement by FISH analysis might be considered as a part of the diagnostic work-up, as MYC rearrangement is most often associated with plasmablastic lymphoma and anaplastic plasmacytoma, but absent in ALK-positive large B-cell lymphoma and PEL." (PMID 33669719, 2021).
anaplastic large cell lymphoma (21 papers, 2009 to 2023). Anaplastic large cell lymphoma (ALCL) is a rare and aggressive peripheral T-cell non-Hodgkin lymphoma, belonging to the group of CD30-positive lymphoproliferative disorders, which affects lymph nodes and extranodal sites. "BATF3 has been reported to induce MYC activity and thereby promote tumor growth in anaplastic large cell lymphoma, consistent with the MYC targets molecular program enriched in cALCL." (PMID 37790936, 2023). "Higher MYC expression enhances crizotinib chemoresistance via autophagy in anaplastic large cell lymphoma." (PMID 34630126, 2021). "Recently, it has been reported that MYC regulates the proliferation of anaplastic large cell lymphoma." (PMID 32587329, 2020). "Ring finger protein 213 (RNF213) has been reported as a fusion partner of ALK and MYC in anaplastic large cell lymphoma and inflammatory myofibroblastic tumor." (PMID 26089344, 2015). "Of note, MYC with STAT3 transcriptionally regulates PD-L1 in ALK-negative anaplastic large cell lymphoma (ALCL)." (PMID 32549409, 2020). "MYC increases SOX2 transcriptional activity, forming a positive-feedback loop involving the Wnt/β-catenin/MYC/SOX2 axis, which defines a highly tumorigenic cell subpopulation in ALK-positive anaplastic large cell lymphomas." (PMID 30688660, 2019). "Recently, it has been reported that BATF3 forms AP-1 complexes with JUN in the MYC promoter and controls MYC expression in cHL (classical Hodgkin lymphoma) and ALCL (anaplastic large cell lymphoma) cell lines, critically supporting their proliferation and survival." (PMID 29661228, 2018). "The frequency of mutations was similar to other reported cases of somatic hypermutations found in Rho/TTF, MYC and BCL6 in large-cell lymphomas (MF was from 0.12 for MYC to 0.69 for BCL6)." (PMID 19478941, 2009). "Moreover, rarer sub-entities such as MYC and BCL2 “double hit lymphomas” (DHL), IRF4-rearranged large cell lymphoma (IRF4-LCL), and Burkitt-like lymphomas with 11q aberration pattern (mnBLL-11q) attracted interest while their relatedness regarding the major classes is still unclear in many respects." (PMID 35884496, 2022).
asthma (21 papers, 2012 to 2025). "Additional miRNAs like hsa-miR-451a, miR-203a-3p, and miR-27a-5p were tied to asthma-related genes including MYC, EGFR, and BMI1, highlighting their involvement in airway inflammation and remodeling." (PMID 40806181, 2025). "In addition, MYC might proof useful as a genetic risk marker for MS and/or asthma." (PMID 35121767, 2022). "Exposure of ASMCs from patients with severe asthma to dexamethasone, either on its own or before stimulation with FCS plus TGF-β, resulted in a larger increase in c-MYC mRNA expression (both P < .001)." (PMID 27484035, 2017). "When PVT1 was targeted with siRNAs in ASMCs from patients with severe asthma, the FCS plus TGF-β– and dexamethasone plus FCS plus TGF-β–induced c-MYC expression was returned to basal levels." (PMID 27484035, 2017). "Moreover, mTORC1 signaling, adipogenesis, MYC target v1, protein secretion, and fatty acid metabolism were significantly influenced by increased ACER3 expression in asthma." (PMID 38297226, 2024). "Furthermore, in ASMCs from patients with severe asthma, dexamethasone increases PVT1 expression, and inhibition of this with siRNAs results in an increase in FCS plus TGF-β–induced cellular proliferation through targeting of the transcription factor c-MYC." (PMID 27484035, 2017).
skin tumors (21 papers, 2004 to 2026). "Mutations in the Hras, Pten, Pi3k, Mdm2, Tp63, Esr, Pgr, and Her2 genes, loss of Cdkn2a, Igf, and Akt, as well as MYC phosphorylation have been identified in DMBA-induced breast, blood, and skin tumor models." (PMID 41426972, 2025). "To examine whether changes in MYC expression occur in skin cancer, we first extracted RNA from 13 human SCC and 5 adjacent skin samples and performed qRT-PCR for cMYC expression." (PMID 32895364, 2020).
cyst (20 papers, 2017 to 2026). A sac-like closed membranous structure that may be empty or contain fluid or amorphous material. "For instance, MYC Proto-Oncogene (MYC) and Cyclin-Dependent Kinase 6 (CDK6) are involved in driving granulosa cell proliferation and activating ovulatory pathways, but their overexpression in the absence of proper differentiation may result in cyst formation." (PMID 40725447, 2025).
gastric adenocarcinoma (20 papers, 2013 to 2026). "BACKGROUND: We aimed to demonstrate that MYC amplification in adenocarcinomas of the stomach (GC) and gastroesophageal junction (GEJ) is of tumor biological significance and exhibits intratumoral heterogeneity." (PMID 42032556, 2026). "Moreover, ANXA1 and MYC tended to co-occur in the same stomach adenocarcinoma samples at the gene expression level (odds ratio between 2 and 10)." (PMID 26760764, 2016). "Gain of MYC copies was found in all gastric adenocarcinoma samples by FISH and qPCR assays." (PMID 23717612, 2013). "We evaluated the effect of MYC mRNA expression and its protein immunoreactivity, as well as copy number variation, promoter DNA methylation, and point mutations, in 125 gastric adenocarcinoma and 67 paried non-neoplastic tissues." (PMID 23717612, 2013). "Clonal high amplification of c-MYC is less frequent in diffuse-type gastric adenocarcinoma (ACP-02) than in ACP-03 and AGP-01 cells, originated from intestinal-type gastric adenocarcinoma." (PMID 27259267, 2016). "In particular, among the 293 cases of gastric adenocarcinoma in TCGA database, MYC and CCNE1 amplification was detected in 11.9% and 10.6% patients, respectively, whereas in the CSF samples of our cohort, the MYC and CCNE1 amplification ratios were 46.7% and 53.3%, respectively." (PMID 37131253, 2023).
monoclonal gammopathy of undetermined significance (20 papers, 2015 to 2024). "Considering the progressive accumulation of genomic abnormalities associated with tumor progression, we wondered if Vk*MYC MM remained dependent on MYC dysregulated expression, which in this model is the driver of progression from monoclonal gammopathy." (PMID 38714690, 2024). "The Vk*MYC genetically engineered mouse model of MM is based on the sporadic AID-induced activation of human MYC in a single germinal center (GC) B-cell, in a mouse strain, C57Bl/6, that spontaneously develops monoclonal gammopathy." (PMID 38714690, 2024). "A MYC activation signature is seen in 67% of MM patients, and this signature influences the progression from monoclonal gammopathy of undetermined significance (MGUS) to MM." (PMID 36880649, 2023). "Activation-induced cytidine deaminase (AID, a marker of monoclonal gammopathy of undetermined significance induction, a precursor of MM) was upregulated in both bone marrow and spleen of both Vk*MYC and WT mice in the 72-week study." (PMID 32050978, 2020). "We examined PVT1/MYC expression using real-time PCR in plasma cells purified from 59 monoclonal gammopathy of undetermined significance (MGUS) and 140 MM patients." (PMID 32992461, 2020). "Deregulation of c-MYC has been suggested to be an important step in disease progression from the asymptomatic monoclonal gammopathy of undetermined significance (MGUS) stage to the symptomatic MM in human and in murine models." (PMID 29262596, 2017). "In fact, both mouse and human data support the notion that a moderate increase in MYC expression would be crucial for the transition from the pre-malignant condition of monoclonal gammopathy of undetermined significance (MGUS) toward frank MM." (PMID 25925570, 2015). "A several-fold increase in c-Myc RNA expression occurs with progression of pre-malignant monoclonal gammopathy of undetermined significance (MGUS) to MM, and this key role for c-Myc in MM is strongly supported by the Vk*MYC mouse model." (PMID 35159039, 2022).
serous ovarian cancer (20 papers, 2013 to 2025). "DL78 preferentially targets chromosomally unstable, MYC-overexpressing cancer cells, a hallmark of high-grade serous ovarian cancer." (PMID 41173942, 2025). "Chromosome 8q24 amplification, including MYC, is widely described to be associated with tumorigenesis, notably in serous ovarian cancer." (PMID 35965534, 2022). "Given previous evidence that HJURP promotes malignant progression and mediates cisplatin sensitivity via MYC in serous ovarian cancer, we focused on MYC for further investigation." (PMID 40290723, 2025). "MYC was found to be one of the most amplified genes in high-grade ovarian serous carcinomas, and the patients bearing MYC-amplified tumors had better overall survival." (PMID 33868369, 2021). "High-grade serous ovarian cancer is characterized by extensive copy number alterations, among which the amplification of MYC oncogene occurs in nearly half of tumors." (PMID 30422115, 2018). "An high-grade serous ovarian cancer (HGSOC) cell line, OVCAR-3 was reprogrammed by transducing Yamanaka four factors OCT4, SOX2, KLF4 and MYC (OSKM) to establish an iOCIC model, iOVCAR-3-OSKM." (PMID 36085021, 2022). "GEO-based analysis of microarray GSE189717 showed ectopic expression of MYC, EGFR, and CCND1 in platinum-resistant high-grade serous ovarian cancer cell lines." (PMID 35739532, 2022). "Significantly high levels of MYC, EGFR, and CCND1 were detected in platinum-resistant high-grade serous ovarian cancer cell lines." (PMID 35739532, 2022). "In support, high expression of MYC mRNA significantly correlated with platinum resistance and shorter PFS in platinum- and gemcitabine-treated serous ovarian carcinoma patients." (PMID 29712888, 2018). "MYC, an oncogene, is amongst the most amplified genes in high-grade serous ovarian cancer (HGSOC), but it has not previously been utilized to drive HGSOC GEMMs." (PMID 39225558, 2024). "To determine whether the relationship between PKA and MYC exists in additional cancers, we applied gene set enrichment analysis (GSEA) to RNASeq data from the TCGA adrenocortical carcinoma and serous ovarian carcinoma data sets." (PMID 36692000, 2023). "To further validate the relevance of MYC, EGFR, and CCND1 to platinum chemotherapy response, we analyzed their differential expression between platinum-sensitive and platinum-resistant high-grade serous ovarian cancer cells based on GEO microarray (GSE189717)." (PMID 35739532, 2022).
colitis (19 papers, 2015 to 2025). Inflammation of the colon. "A reported article has mentioned that though miR-34b-5p upregulation represses colitis-associated cancer aggravation, c-MYC overexpression is able to abrogate the suppressed malignant phenotypes." (PMID 34623601, 2022). "To evaluate the effects of the pharmacological blockade of both p38α and MEK/ERK on the c-MYC protein levels in vivo, we used the azoxymethane (AOM)/dextran sodium sulfate (DSS) colitis-associated-carcinoma murine model, which is considered a highly reproducible and reliable CRC model." (PMID 36230763, 2022). "Research indicated that regulating the stability of MYC could suppress colitis-induced tumourigenesis." (PMID 36532769, 2022).
Hyperglycemia (19 papers, 2009 to 2026). An increased concentration of glucose in the blood. "STAT3 is known to be an upstream regulator of MYC, and its association with hyperglycemia has been reported in the kidneys, lungs, and heart." (PMID 32609742, 2020). "In the present study, hyperglycemia accelerated PanIN progression, with increases in pSTAT3 and MYC levels." (PMID 32609742, 2020). "In murine pancreatic islet cells, mRNA expression of MYC was increased in vitro under supraphysiological glucose concentrations, and during hyperglycaemia in vivo." (PMID 32477515, 2020). "In conclusion, hyperglycemia, on a Kras-mutant background, aggravates the PanIN progression, which is accompanied by elevated pSTAT3 and MYC expression." (PMID 32609742, 2020). "Importantly, c-MYC transgenic mice developed hyperglycaemia after 6 h of fasting and demonstrate considerably impaired glucose tolerance in the glucose tolerance test (GTT)." (PMID 35008356, 2021). "Hyperglycemia strengthened the STAT3 phosphorylation, which was accompanied by elevated MYC expression in Kras-mutant cells." (PMID 32609742, 2020). "The metabolic disturbances and hyperglycemia in diabetic ischemic heart disease might alter the activity of kinases and transcription factors like DNA-PK, CDC2, MYC, SP1, and CREB1, exacerbating cardiac dysfunction." (PMID 39420368, 2024). "To clarify whether the changes in the expression of pSTAT3, MYC, and pERK were only in vitro phenomena or these changes play important roles in PanIN progression in vivo, we performed immunostaining for pSTAT3, MYC, and pERK in precancerous PanINs, with or without hyperglycemia." (PMID 32609742, 2020). "Hyperglycemia did not activate ERK, the major Kras effector, but strengthened the phosphorylation of STAT3 and the expression of MYC." (PMID 32609742, 2020).
rectal cancer (19 papers, 2009 to 2025). A primary or metastatic malignant neoplasm that affects the rectum. "GSEA analysis for TCGA database indicated that STK16 positively activated the MYC signaling pathway in both colon and rectal cancers." (PMID 38622518, 2024). "Survival analysis of MYC mRNA in colon and rectal cancer patients (the PrognoScan)." (PMID 33193630, 2020). "Additionally, previous literature has revealed that TCF3 and TCF4 are overexpressed in rectal cancer and they control MYC expression in colorectal cells." (PMID 27818995, 2016). "Furthermore, the m6A modification-based risk score system is associated with activation of distinct signaling pathways, such as DNA repair, epithelial-mesenchymal transition, G2M checkpoint and the MYC pathway, that may contribute to the progression of rectal cancer." (PMID 34149792, 2021). "We found that MMP9, MYC, and VEGFA were upregulated in the rectal cancer group compared with normal tissue." (PMID 28689994, 2017).